CXCL14 (C-X-C motif chemokine ligand 14)
Description:
Potent chemoattractant for neutrophils, and weaker for dendritic cells. Not chemotactic for T-cells, B-cells, monocytes, natural killer cells or granulocytes. Does not inhibit proliferation of myeloid progenitors in colony formation assays.
Synonyms: MIP2G; NJAC; SCYB14; BRAK; bolekine; Kec; MIP-2g; BMAC; KS1
Tractability: Antibody: UniProt places it where antibodies can reach, with medium confidence; UniProt predicts a signal peptide or a membrane-spanning region; its Gene Ontology location is reachable by antibodies, with medium confidence. PROTAC: UniProt records ubiquitination sites on it.
Gene: Protein-coding gene on chromosome 5 (135,570,679 to 135,579,279, reverse strand). Ensembl gene ENSG00000145824.
Subcellular location: Secreted
Gene Ontology:
Molecular function: protein binding; chemokine activity
Biological process: antimicrobial humoral immune response mediated by antimicrobial peptide; cell-cell signaling; chemotaxis; signal transduction; cell chemotaxis; immune response
Cellular component: Golgi apparatus; extracellular region
Genetic constraint (gnomAD): Loss-of-function variants: 9 observed, 15.92 expected, observed/expected ratio (o/e) 0.57, 90% interval 0.34 to 0.99. The upper end of that interval is the gene's LOEUF score, 0.99, which puts it in group 4 of 6, group 1 being the genes least tolerant of losing a copy. Missense variants: 111 observed, 137.85 expected, observed/expected ratio (o/e) 0.81, 90% interval 0.69 to 0.94. Synonymous variants: 55 observed, 50.83 expected, observed/expected ratio (o/e) 1.08, 90% interval 0.87 to 1.36.
Homologues: Orthologues: chimpanzee CXCL14 (100% identical), macaque CXCL14 (96% identical), pig CXCL14 (96% identical), rat Cxcl14 (96% identical), mouse Cxcl14 (95% identical), guinea pig CXCL14 (94% identical), dog CXCL14 (93% identical), tropical clawed frog cxcl14 (68% identical), zebrafish cxcl14 (54% identical).
Diseases named in the same sentence as CXCL14 in open-access papers:
CXCL14 is named in the same sentence as 175 diseases in open-access papers, as found by Europe PMC text mining. Sharing a sentence is not in itself a finding about the gene and the disease. The quoted sentences say what the papers report.
breast carcinoma (57 papers, 2011 to 2026). "CXCL14 encodes secreted proteins involved in immuno-regulatory and inflammatory processes, which promotes tumor growth in breast cancer, and COX6C serves as a bio-marker for cancer therapy." (PMID 38783355, 2024). "CXCL14 encodes secreted proteins involved in immunoregulatory and inflammatory processes, promoting tumor growth in breast cancer." (PMID 39228303, 2024). "A high expression of CXCL14 is associated with better overall survival in colorectal, cervix, head and neck, endometrial, and breast cancer." (PMID 37688629, 2023). "As aggressive breast cancers have been diagnosed in younger women, we then evaluated the association between CXCL14 expression and age." (PMID 36012586, 2022). "Analysis of human breast-cancer datasets showed that low CXCL14 expression levels were associated with poor survival rates in patients with breast cancer, particularly for TNBC subtypes." (PMID 36012586, 2022). "In particular, in prostate and breast cancer, CXCL14 is produced by cancer associated fibroblasts (CAFs) in the tumor microenvironment and contributes to tumor growth and invasion." (PMID 31117166, 2019). "In these cells, the exogenous supplementation of CXCL14 induces ERK1/2 phosphorylation, as it does in breast carcinoma, where CXCL14 is secreted in the microenvironment by cancer associated fibroblasts." (PMID 31117166, 2019). "CXCL14 has a demonstrated role as a pro-tumoral chemokine produced in the tumor microenvironment of breast carcinoma by cancer associated fibroblasts (CAFs)." (PMID 31117166, 2019). "In breast cancer cells, reactive oxygen species (ROS) caused by interrupted mitochondrial respiratory chain increases CXCL14 expression through activation of the activator protein-1 (AP-1)." (PMID 26733763, 2016). "However, in pancreatic and breast cancer, high stromal CXCL14 expression is associated with increased invasiveness, leading to poor survival in patients." (PMID 35769715, 2022). "Moreover, the CXCL14 gene was selected as a benchmark to evaluate the risk of recurrence in breast cancer." (PMID 34696665, 2021). "In Cluster 5 (IDC), upregulated genes such as CXCL14, S100A11, CCND1, and AGR2 are linked to breast cancer progression, metastasis, and therapeutic resistance." (PMID 41182757, 2025). "On the other hand, cluster 4 (IDC) exhibits the suppressive influence of the chemokine CXCL14 on tumor growth and metastasis in human breast cancer cells, as evidenced in both in vitro and in vivo studies." (PMID 40304359, 2025). "For breast cancer normal-tumor differentiation, CXCL14, MSLN, LCN2, and MED1 emerged as significant predictors, supported by evidence of their differential expression and involvement in tumor progression." (PMID 41139924, 2025). "Breast cancer cells have also been found to secrete chemokine (C-X-C motif) ligand 14 (CXCL14), a chemokine ligand for the GPR85 receptor, which activates fibroblasts through the ERK1, AKT, and neddylation pathways." (PMID 39623094, 2024). "In the task of identifying SVGs, STMVGAE accurately identified the CXCL14 in domain 17, which had been proven to have prognostic significance in breast cancer." (PMID 39717398, 2024). "Another study also shows that CXCL14-expressing CAFs promote breast cancer epithelial-to-mesenchymal transition, invasion, and metastasis by interacting with the ACKR2 receptor." (PMID 39334513, 2024). "CAFs exhibiting increased expression of the epithelial chemokine CXCL14 induce EMT in breast cancer cells, thereby facilitating their migration and invasion." (PMID 38273859, 2023). "Although CXCL14 is a relatively novel gene in the chemokine family, it has long been reported that CXCL14 is closely related to the occurrence of breast cancer, liver cancer, lung cancer and other cancers." (PMID 37835641, 2023). "By targeting CCL11 and CXCL14, MiR-29b encore in CAFs decreases breast cancer cell survival and metastasis." (PMID 36247409, 2022).
breast carcinoma (continued). "Altogether, these analyses support a positive correlation of CXCL14 with host anti-tumor immunity of breast cancer, particularly in TNBC subtype." (PMID 36012586, 2022). "CXCL14 is decreased in TNBC, and overexpression of CXCL14 attenuates breast-cancer progression through regulating immune profiles of the tumor microenvironment in a T cell-dependent manner." (PMID 36012586, 2022). "Our studies demonstrate that high CXCL14 levels correlate with better survivals of breast-cancer patients." (PMID 36012586, 2022). "The positive correlation of CXCL14 levels with better survival in breast-cancer patients is consistent with several publications: CXCL14 prolonged survivals in glioma and in colorectal carcinoma." (PMID 36012586, 2022). "In a cohort of 51 breast cancer patients GSE18864 and in the TCGA breast cancer dataset, CXCL14 expression was overall higher in older breast-cancer patients than younger patients post chemotherapy." (PMID 36012586, 2022). "Elevated levels of CXCL14 are shown to be correlated with improved survival in breast-cancer patients based on histological staining." (PMID 36012586, 2022). "We, next, investigated the correlation between CXCL14 expression and immune profiles in human breast cancer." (PMID 36012586, 2022). "The correlation between CXCL14 expression and clinical features was further investigated among different breast-cancer subtypes." (PMID 36012586, 2022). "To investigate the clinical relevance of CXCL14 in breast cancer, we examined the correlation between CXCL14 expression and survival of breast cancer patients using publicly available human breast-cancer datasets." (PMID 36012586, 2022). "The cancer inhibitory effect by CXCL14 have been reported in various cancer types, including breast cancer." (PMID 36012586, 2022). "For instance, Wang demonstrated that C-C motif chemokine-17 (CCL-17) was secreted from CXCL14-activated fibroblasts as a regulatory factor of the CXCL14-triggered breast carcinoma cell EMT and metastasis." (PMID 34789307, 2021). "The CXCL14 expression was significantly higher in breast cancer patients with lymph node metastasis, suggesting this protein as a new prognostic marker for lymphatic metastasis." (PMID 34833492, 2021). "On the contrary, CXCL14 was reported to promote cancer cell motility by regulating Ca2+ release in breast cancer." (PMID 34744744, 2021). "Recently, Xu and colleagues identified and validated a cell subpopulation of breast cancer cells with a high expression level of CXCL14 in the positive lymph nodes of breast cancer patients." (PMID 34833492, 2021). "Gu and her colleagues found that the overexpression of CXCL14 inhibited the proliferation and invasion of breast cancer cells, and weakened the growth and lung metastasis of xenograft tumors." (PMID 32253815, 2020). "CXCL14, a 13 kDa chemokine, is involved in the progression and metastasis of many malignant cells, such as prostate cancer, breast cancer, and lung carcinoma cells." (PMID 32708730, 2020). "CXCL14 promotes the progression and metastasis of breast cancer, lung cancer, and pancreatic cancer." (PMID 32708730, 2020). "CXCL14 and LIFR are associated with the prognosis of Luminal A, HER-2 positive breast cancer and TNBC." (PMID 31781173, 2019). "Examples include miR‐30c‐2‐3p in breast cancer, miR‐218 in hepatocellular carcinoma, CXCL14 in colorectal carcinoma, and SERPINH1 in clear cell renal cell carcinoma." (PMID 30913346, 2019). "CXCL14, a chemokine, induces proliferation,migration, and invasion of breast cancer cell lines and wasfound to be increased in ductal carcinoma in situ comparedto normal breast tissue, indicating a protumorigenic andprometastatic role in breast cancer." (PMID 30930637, 2019). "CCL11 and CXCL14 from the CAFs will exert on breast cancer cell and then promotes cell proliferation and metastasis." (PMID 28465475, 2017).
breast carcinoma (continued). "Calcitriol (10 nM) reduced invasion of MDA-MB-231 breast cancer cells by 59.8%, and CXCL14 (10 ng/ml) increased their invasiveness up to 151.9%." (PMID 28003019, 2016). "It is also known that the phosphorylation of p38MAPK leads to activation of AP-1, which was shown to be essential for elevation of CXCL14 expression as stimulated by ROS in breast cancer cells." (PMID 26733763, 2016). "In prostate and breast cancer, it is reported that the tumor-supportive effect of fibroblast-derived CXCL14 depends on nitric oxide synthase NOS1 mediated signaling mechanisms." (PMID 26733763, 2016). "The chemokine CXCL14 has been reported to play an important role in the progression of many malignancies such as breast cancer and papillary thyroid carcinoma, but the role of CXCL14 in colorectal carcinoma (CRC) remains to be established." (PMID 23294544, 2013). "Additionally, ACKR2 has been identified as a receptor for exogenous CXCL14 in lung and breast cancers, where it contributes to the activation of tumor cell invasion and migration." (PMID 40898244, 2025). "Additionally, ECM‐mCAFs, which highly express the immune cell‐attracting factor CXCL14, are positively correlated with overall patient survival rates in breast cancer." (PMID 41164803, 2025). "Recent studies suggest that CXCL14 derived from CAFs may promote malignant progression in ovarian and breast cancers." (PMID 40898244, 2025). "CXCL14 was also found to promote breast cancer cell progression by another orphan GPCR, GPR8534." (PMID 38184723, 2024). "The previous study analyzed the data in GSE158399 and found the elevated expression level of CXCL14 in PLs, which might be valuable in predicting the prognosis of breast cancer with lymph node metastasis." (PMID 37744272, 2023). "In addition, the activation of cancer-associated fibroblasts through the CXCL14/GPR85 pathway has been shown to leads to EMT and progression in breast cancer." (PMID 37056937, 2023). "Finally, high CXCL14 correlates with increased patient survival, suggesting CXCL14 as a biomarker for prognosis for breast cancer patients." (PMID 36012586, 2022). "We also examined the relationship between CXCL14 and OS in different breast-cancer subtypes." (PMID 36012586, 2022). "In summary, CXCL14 is decreased in breast cancer especially in the basal subtype." (PMID 36012586, 2022). "Together, these data demonstrate the inhibitory role of CXCL14 on breast-cancer progression." (PMID 36012586, 2022). "Moreover, the heterogeneity between the primary tumor and metastases in lymph nodes was assessed using scRNA-seq, and a novel cell subpopulation called CXCL14 cancer cells was identified in the positive lymph nodes of breast cancer patients." (PMID 34745998, 2021). "Moreover, CXCL14 expression is downregulated in breast cancer, and CXCL14 overexpression inhibits cell growth and invasion in vitro and attenuates tumor growth and pulmonary metastasis of breast carcinoma cells in vivo." (PMID 34789307, 2021). "Moreover, CXCL14 expression was reported to be up-regulated by ROS and promoted cell motility in breast cancer cell lines." (PMID 34744744, 2021). "Therefore, CXCL14 can inhibit the growth and metastasis of breast cancer cells, suggesting that CXCL14 is an anticancer chemokine in breast cancer." (PMID 32253815, 2020). "Recent studies have suggested that the G protein-coupled receptor GPR85 and atypical chemokine receptor 2 (ACKR2) could be the target of CXCL14 in breast cancer cells." (PMID 32708730, 2020). "Further molecular mechanism exploration indicated CCL11 and CXCL14 could active p38-STAT1 pathway in breast cancer cells." (PMID 28465475, 2017). "Here we show that its expression could distinguish ER− tumors stratified by HER2 status, and have CXCL14 sharing the same expression pattern with hsa-miR-365, which together suggests the differential regulation of chemokines in breast cancer subtypes." (PMID 27786176, 2016).
breast carcinoma (continued). "Finally, disrupting the mitochondrial respiratory chain leads to increased ROS and has been shown to increase the motility and invasiveness of breast cancer cells through mechanisms mediated by cytokines such as CXCL14." (PMID 21605372, 2011). "Also, high CXCL14 correlates with better survival in patients with breast cancer, and could serve as a prognostic biomarker for clinical features." (PMID 36012586, 2022). "MiR-29b could inhibit breast cancer cell migration via CCL11 or CXCL14 from CAFs." (PMID 28465475, 2017). "In primary breast cancer samples, there were higher levels of iCAFs, which were identified by high expression of cytokines such as CXCL12, CXCL14, and IL686." (PMID 40858590, 2025). "Recent studies have shown that cancer cell-intrinsic CXCL14 also promotes EMT and distant metastasis in breast cancer, lung cancer, and osteosarcoma, apart from CAF-derived CXCL14." (PMID 39358777, 2024). "The CXCL14, COX6C, and CRISP3 have been verified are highly expressed genes of invasive dual carcinoma (IDC) in breast cancer." (PMID 39764614, 2024). "CAFs with upregulated epithelial chemokine CXCL14 induce EMT in breast cancer and facilitate the migration and infiltration of breast cancer cells." (PMID 38273859, 2023). "High levels of CXCL14 showed better overall survival (OS), recurrence-free survival (RFS), and distant metastasis-free survival (DMFS) in patients with breast cancer, indicating CXCL14 as a prognostic marker for favorable clinical outcomes in breast cancer." (PMID 36012586, 2022). "It has been shown that CAF-secreted CXCL14 suppresses epithelial markers and induces mesenchymal phenotypes in MCF-7 breast cancer cell-bearing mice, leading to the colonization of MCF-7 cells in the lungs of mice." (PMID 35677043, 2022). "Several differentially expressed mRNAs in HER2-positive breast cancer (including CXCL2, CXCL12, CXCL10, CXCL11, CXCL9 and CXCL14) were enriched in the biology processes of chemokine receptor binding and chemokine activity." (PMID 34257572, 2021). "ATAC-seq of the positive and negative lymph node samples further revealed the chromatin accessibility profile and identified potential TFs related to CXCL14 cancer cells, including ZNF467, bZIP, EBF1, and PIT1, in the lymph node metastases of breast cancer." (PMID 34745998, 2021). "Activation of GPR85 by CXCL14 triggered ERK1/2 and AKT pathway activation, which promoted breast cancer cell progression." (PMID 32708730, 2020). "In another study, a signature of four immune-related genes (APOD, CXCL14, IL33, and LIFR) was correlated with breast cancer prognosis." (PMID 33092068, 2020). "During the preparation of our manuscript, a paper was published, which describes the role of fibroblast-derived CXCL14 in EMT and metastasis of breast cancer, and identifies the GPCR ACKR2 as a mediator for CXCL14 action." (PMID 31117166, 2019). "We found that fibroblasts activated by co-cultured breast cancer cells produced higher levels of some chemokines like CCL11, CXCL14, which accelerated breast cancer cell growth and induced drug resistance and metastasis." (PMID 28465475, 2017). "Given that CYP24A1 and CXCL14 were the top upregulated genes, we further examined their role in MDA-MB-231 breast cancer cell invasion." (PMID 28003019, 2016). "Previous studies indicate that downregulation of CXCL14 is associated with prognosis in gastric cancer patients, MT1X may aid in the prognostic discrimination of oral squamous cell carcinoma cases, and MARCO expression is associated with breast cancer survival and risk of recurrence." (PMID 27567667, 2016). "Furthermore, ACKR2 is a receptor responsible for CXCL14-induced EMT and metastasis in breast cancer." (PMID 37056937, 2023). "In addition, in single-cell RNA-seq data of human breast cancer (GSE176078), we found a significantly high CXCL14 expression correlated with a low percentage of CD25+ Treg." (PMID 36012586, 2022).
breast carcinoma (continued). "CXCL14 (earlier designated as BRAK, MIP-2γ, BMAC, or KS1), was identified in this study as one of the chemokines that had been previously shown to play a key role in breast cancer." (PMID 31781173, 2019). "For example, we recently found that overexpression of the chemokines CXCL14 and CCL17 in mammary fibroblasts could enhance proliferation, migration, invasion of breast cancer epithelial cells, and contribute to chemo-resistance and disease relapse." (PMID 30925930, 2019). "It was found that miR-29b could inhibit breast cancer cell survival and also suppressed cell growth by CCL11 and CXCL14 stimulation." (PMID 28465475, 2017). "Here, to know whether there are differences of miR-29b down-regulation on drug resistance of breast cancer cells, MCF-7 cells were treated with CM-CAFs, CM-CAFs/miR-29b-1 or CM-CAFs/miR-29b-2 and exposed to paclitaxel (10uM) or CCL11 or CXCL14." (PMID 28465475, 2017). "Breast cancer cell invasion ability was also inhibited by miR-29b, which could suppress CCL11 and CXCL14 enhanced invasion." (PMID 28465475, 2017). "For example, CXCL14 derived from CAFs in prostate cancer and SDF1/CXCL12 derived from CAFs in breast cancer called up macrophages, endothelial cells derived from bone marrow source, M2 mononuclear cells to the tumor tissue respectively, which assisted the tumor formation new blood and lymph vessels." (PMID 23577100, 2013).